TTF1 (transcription termination factor 1)
Diseases named in the same sentence as TTF1 in open-access papers (continued):
Sharing a sentence is not in itself a finding about the gene and the disease.
thyroid cancer (continued). "TTF-1 plays an important role in the immunopathological diagnosis of lung and thyroid cancers." (PMID 29904902, 2018). "Given the important role TTF1 plays in maintaining thyroid architecture and function, it is not surprising that any abnormalities in the gene and its product contribute to the development of thyroid carcinoma." (PMID 28117295, 2017). "However, that rate drops in poorly differentiated thyroid carcinomas to 86% for TTF-1, 57% for thyroglobulin, and 86% for CK7." (PMID 27774331, 2016). "131I scan and serum thyroglobulin are widely employed during the follow up of thyroid cancer and in the assessment of the best therapy to use after surgery, while immunohistochemical stain for thyroglobulin and TTF-1 is often essential in pathologic diagnosis as it has been in our experience." (PMID 25358556, 2014). "Therefore, we decided to assess the potential contribution of TTF-1 and TTF-2 genes as sources of genetic susceptibility to thyroid cancer in this particular group." (PMID 22481925, 2012). "KTC-1 cells show relatively higher PAX-8 and TTF-1 transcripts among thyroid cancer cell lines." (PMID 21556376, 2011). "In Case 6, for example, where the patient was strongly suspected of having either a primary lung or thyroid carcinoma due to positive TTF-1 staining, the TOO Test result of breast carcinoma, while unexpected, had not been absolutely ruled out by clinical factors." (PMID 20205775, 2010). "The simultaneous positivity for thyroid specific factor TTF-1 and onfFN suggest they might represent putative thyroid cancer stem-like cells." (PMID 18958156, 2008). "The mechanisms by which TTF1 contributes to thyroid carcinoma still remains unclear." (PMID 28117295, 2017). "Immunohistochemistry revealed tumor marker patterns characteristic of malignancy, including parafibromin and E-cadherin loss and positivity for markers such as galectin-3 and cyclin D1 in parathyroid cancers and TTF1 and CK19 in thyroid cancer." (PMID 40142758, 2025). "Cribriform morular thyroid carcinoma can be differentiated from common follicular-cell-derived tumors by the absence of typical mutations; the presence of nuclear and cytoplasmic expressions of β-catenin; the presence of TTF-1, except in morular areas; and the absence of thyroglobulin." (PMID 38835742, 2024). "This allowed NIS, PAX-8, TTF-1, TTF-2, and TSHR gene expression to promote redifferentiation of thyroid cancers." (PMID 33995657, 2021). "Metastatic tumors that contain clear cells are most likely renal cell carcinoma, clear cell breast carcinoma or thyroid carcinoma and, therefore, immunomarkers such as RCC, CD10, PAX8, ER/PR, TTF-1 are useful." (PMID 32642935, 2021). "Some proteins' alteration was found in thyroid cancer, such as CK19, TG, Ki67, Calcitonin, TTF-1, BRAF, RET, HBME-1, SERPINA1, TfR1/CD71, FHL1 and galectin-3." (PMID 22188859, 2011). "Immunohistochemical results of the dedifferentiated tumor cells in this case showed that TG and TTF-1 were negative, suggesting that conventional immunohistochemical results should not be relied upon for diagnosis of thyroid cancer metastasis." (PMID 40502629, 2025). "TTF‐1, while often expressed in follicular‐derived thyroid carcinomas and pulmonary neuroendocrine tumors, is usually absent in MTC." (PMID 41320889, 2025). "Primary thyroid carcinomas typically express TG, TTF-1, and PAX8, whereas these markers are generally absent in metastatic lesions." (PMID 41018104, 2025). "Further, the tumor was negative for thyroglobulin and TTF-1 (excluding thyroid carcinoma), TTF-1 (arguing against a lung primary), and Villin (which helps exclude a carcinoma of digestive tract origin)." (PMID 41584573, 2025). "The patient had a past history of papillary thyroid cancer but TTF-1 was negative and the nuclear findings were also inconsistent with thyroid cancer recurrence." (PMID 24397776, 2014).
thyroid cancer (continued). "These biomarkers, such as CK19, TG, Ki67, Calcitonin, TTF-1, BRAF, RET, HBME-1, and galectin-3, have been translated into clinical practice which offered significant improvement in the preoperative diagnosis of thyroid cancer." (PMID 22188859, 2011). "Furthermore, dysregulation of three transcription factors (TTF-1, hepatocyte nuclear factor 3 β (HNF3β)/forkhead box A2 (FoxA2), and CCAAT/enhancer binding protein β (C/EBPβ)) was examined in thyroid carcinoma cells." (PMID 18682709, 2008). "Next, we evaluated the expressions of thyroid transcription factor (TTF)-1 and − 2 as well as the expression of differentiation related genes, such as thyroid stimulating hormone receptor (TSH-R), thyroglobulin (TG) and sodium/iodide symporter (NIS) in thyroid cancer cell lines." (PMID 37684566, 2023). "It is a sensitive marker for aggressive types of thyroid carcinomas, such as anaplastic follicular cell-derived thyroid carcinoma, which could be positive even when TTF-1 or thyroglobulin are negative." (PMID 35328664, 2022). "The inhibition of mTOR promotes redifferentiation of thyroid cancer cells by upregulating NIS mRNA and protein expression, resulting in elevated iodine uptake through increased transcription at the level of thyroid transcription factor-1 (TTF1), which indicates TTF1 dependence for NIS expression." (PMID 31533238, 2019). "The suppression of TTF1 could favor the re-expression of the tumor suppressor ABI3, as previously published, thus supporting the cell death mechanism mediated by deacetylase inhibitors in thyroid cancer cells." (PMID 29561759, 2018). "The majority of thyroid carcinomas are markedly positive for TTF-1 and TG, although these two proteins may not be expressed by certain poorly differentiated or sarcoma-like thyroid carcinomas." (PMID 24932236, 2014). "Negative immunohistochemical staining for TG and TTF-1 in the thyroid lesions and similar staining results for ER, PR and CerbB-2 in breast and thyroid lesions may aid the diagnosis of thyroid carcinoma derived from metastatic breast cancer." (PMID 23833651, 2013). "The thyroid specific biomarkers of TTF-1 and PAX8 are usually positively expressed in primary thyroid cancer and were absent in our case." (PMID 37032350, 2023). "Immunohistochemically, the tumor is typically positive for PAX8 and negative for PAX2, TTF-1, and thyroglobulin; TTF-1 or thyroglobulin is required to rule out metastases from thyroid cancer." (PMID 29053609, 2017). "Immunohistochemistry result were negative for TTF-1, Thyroglobulin, CD7 and CD20 which ruled out non-small cell lung adenocarcinoma, thyroid cancer and gastrointestinal tract cancer respectively." (PMID 29147330, 2013). "IHC staining of the tumor in the neck showed diffuse expression of PAX8 and TTF1, indicating thyroid origin, and negative staining for thyroglobulin, calcitonin, PTH, and GATA3, which support a diagnosis of an oncocytic poorly differentiated thyroid carcinoma." (PMID 40277780, 2025). "That could explain why most undifferentiated thyroid carcinomas have little to no TG or TPO proteins, both targets of TTF1 transcription factor activity." (PMID 28117295, 2017).
small cell carcinoma (47 papers, 2003 to 2026). A neuroendocrine carcinoma composed of small malignant cells which are often said to resemble "oat cells" under the microscope. "Biopsy of the lung mass revealed combined small cell carcinoma with an adenocarcinoma component (TTF-1+/CK7+)." (PMID 41256964, 2025). "Disease progression occurred after 12.5 months, and repeat lung biopsy revealed small cell carcinoma (TTF-1+/synaptophysin+/INSM1+; Ki-67 85%)." (PMID 41256964, 2025). "The prevalence of thyroid transcription factor-1 (TTF-1) and napsin A expression are poorly characterized in lung core biopsies of small cell carcinoma." (PMID 37139017, 2023). "While nuclear moulding, inconspicuous nucleoli and brisk mitotic activity along with positive neuroendocrine markers help in the diagnosis of small cell carcinoma, a note of caution is TTF-1 can be positive in both small cell carcinoma and adenocarcinoma." (PMID 36200017, 2022). "Small cell carcinoma is distinguished with the consistent positive immunoreactivity to cytokeratins, and reactivity for IHC markers such as chromogranin and TTF-1 supports the diagnosis of small cell carcinoma." (PMID 23762725, 2013). "On the contrary, TTF-1 expression was observed in 73.6% of small-cell carcinomas, in 23.5% of large-cell carcinomas and in 66.6% of atypical carcinoids." (PMID 21811254, 2011). "The results supported the cytological morphological diagnoses in a case of small cell carcinoma that was positive for TTF-1." (PMID 20806071, 2010). "In particular, TTF-1 expression was observed in a large proportion (80%) of small cell carcinomas, in agreement with previous reports." (PMID 12698189, 2003). "This is in distinction from TTF-1, which is also expressed in a large proportion of small cell carcinomas." (PMID 12698189, 2003). "TTF-1 immunostain results were available in 173 of the 232 cases of confirmed small cell carcinoma." (PMID 37139017, 2023). "TTF-1 expression in small cell mammary carcinoma has been reported in approximately 20% of cases, but not diffuse strong nuclear staining as is frequently seen in small cell carcinoma of lung origin." (PMID 38027104, 2023). "TTF‐1 is highly positive in extrapulmonary small cell carcinomas (especially, in small cell carcinoma of the prostate, positive in 63.3%) and cannot be used to distinguish between lung primary and non‐lung primary in the case of small cell carcinomas." (PMID 37261050, 2023). "In addition, immunoreactivity with TTF-1 and neuroendocrine markers (Syn, CgA, etc.)will support the diagnosis of small cell carcinoma." (PMID 36290813, 2022). "TP63 and TTF-1 are useful for distinguishing both small cell carcinomas as well as AC from SCC." (PMID 35584089, 2022). "Up to 33–39% of small-cell NECs of urinary bladder demonstrate positive staining for TTF1." (PMID 35804996, 2022). "TTF-1 is a highly sensitive marker for extrapulmonary small cell carcinoma including NE/SC." (PMID 34884545, 2021). "CD56 and TTF-1 positivity are seen in small cell carcinoma and carcinoids." (PMID 27034865, 2016). "Therefore, the value of TTF-1 for origin-diagnosis of small cell carcinoma seems to be dispensable, especially as the therapeutic approaches in cases of SCC do usually not differ according to the origin if the primary tumor site." (PMID 25889870, 2015). "Up to 53% of extra-pulmonary small cell carcinomas are known to express TTF-1 as well." (PMID 25671134, 2015). "Hence, a wider range of immunohistochemical markers, including chromogranin and TTF-1 to support a diagnosis of small cell carcinoma, and CD99, vimentin, or FLI1 for PNET should be used for the differential diagnosis." (PMID 25475214, 2014). "However, small cell carcinomas arising from the lung frequently express TTF-1 while those arising from other sites may occasionally also express TTF-1." (PMID 22263108, 2012).
small cell carcinoma (continued). "However, it must be kept in mind the possibility of the presence of relatively rare and highly debated entities such as the primary intracranial neuroendocrine carcinoma arising in sellar region (which is TTF1−)⁠ or the small cell carcinoma of unknown primary (SCUP, which is TTF1+) ⁠." (PMID 36799985, 2023). "In January 2020, repeat biopsy was performed, and the results of immunohistochemistry (IHC) staining showed TTF-1 (+), CK7 (+), napsin A (+), syn (+), and CD56 (+), with a Ki-67 (+) index 80% of small cell carcinomas." (PMID 34397927, 2021). "The pathological type of the present case was oat cell carcinoma and the tumor cells were immunoreactive for pancytokeratin and CD56 and focally immunoreactive for synaptophysin and TTF-1." (PMID 26137338, 2015). "While TTF-1 is not usually considered a conventional marker for diagnosing small cell carcinoma in most centers, it is positive in most of them." (PMID 39392394, 2024). "Lung tumors with morphology suggestive of small cell carcinoma that is negative for TTF-1 should prompt consideration of a wider differential diagnosis." (PMID 37139017, 2023). "In the case of small cell carcinoma, expression of thyroid transcription factor 1 (TTF-1) (seen in up to 50% of small cell carcinomas) and proliferation index of >95% in the absence of melanoma markers can help in the differential diagnosis." (PMID 36407184, 2022). "When a thyroid primary is ruled out, TTF-1 expression is both sensitive and specific for primary adenocarcinomas, bronchioloalveolar carcinomas, and small-cell carcinomas." (PMID 36039229, 2022). "Small-cell carcinomas are positive for IHC, CK, TTF1, and neuroendocrine markers but negative for desmin." (PMID 34193155, 2021). "Interestingly, the results of immunohistochemistry (IHC) staining showed positivity for TTF-1 (+), CK7 (+), napsin A (+), syn (+), and CD56 (+), with a Ki-67 (+) index of 80% of small cell carcinomas." (PMID 34397927, 2021). "This demonstrated metastatic small-cell carcinoma positive for pan-cytokeratin (panCK) and thyroid transcription factor 1 (TTF1), but negative for other traditional markers of small-cell carcinoma such as 34BE12, CD56, synaptophysin, and chromogranin." (PMID 28487881, 2017). "Staining of several markers like CKAE1/3, CK7, TTF-1 and CD-X2 of the small cell carcinoma lesions were negative, indicating that these cells have no extrarenal origin (data not shown)." (PMID 28499369, 2017). "TTF-1 positivity is frequently found in non-squamous carcinomas, small cell carcinomas, large cell carcinomas, as well as typical and atypical carcinoids of the lung." (PMID 26854147, 2015). "The original breast cancer was negative for TTF-1 and chromogranin.The left-sided mass was resected, and final surgical pathology showed a poorly-differentiated small cell neuroendocrine carcinoma, measuring 2.5 × 2.5 × 1.8 cm." (PMID 25671134, 2015). "More specifically, Merkel cell carcinoma is positive for the immunohistochemical antibodies to CK20 and NF and negative for TTF1 while small cell carcinoma is positive for TTF1 and negative for CK20 and NF." (PMID 24555167, 2014). "Although SCCOHT is morphologically similar to small cell carcinomas from other sites, its common expression of WT1 and lack of thyroid transcription factor (TTF)-1 allows it to be distinguished from other small cell cancers." (PMID 23433318, 2013). "In the case of small cell carcinoma with TTF-1 positivity, lung origin is favored, but this is not entirely definitive." (PMID 22263108, 2012). "TTF-1 can be positive in up to half of small cell carcinomas and is not found in the poorly differentiated adenocarcinomas." (PMID 22110988, 2011). "Extrapulmonary small cell carcinoma stains positive for TTF-1 while other extrapulmonary neuorendocrine tumors do not." (PMID 18817561, 2008).
small cell carcinoma (continued). "In environments where lung core biopsies are relatively less frequent, finding that a presumed small cell carcinoma is TTF-1 negative may be disconcerting and may prompt an external review." (PMID 37139017, 2023). "Clinical and chest CT findings are more important in establishing a metastasis than immunohistochemistry, because TTF1 does not reliably differentiate the two primaries as TTF1 may be positive in extrapulmonary small cell carcinoma." (PMID 22666633, 2012). "Biopsy specimen stained positive for CK, CD56, NSE, BcL2, Synaptophysin, PAX-5, and TTF-1, but negative for Chromogranin, CD57, and NFP; consistent with small cell carcinoma." (PMID 30428872, 2018).
thyroid (40 papers, 2008 to 2026). "The tumor expressed thyroid markers (TTF-1, PAX-8, thyroglobulin) and renal cell markers (colloidal iron, parvalbumin, CD117) with peripheral mitochondrial accentuation by anti-mitochondrial staining." (PMID 41518426, 2026). "Thyroid transcription factor 1 (TTF1) is considered a useful immunohistochemical marker for diagnosing thyroid and lung tumors, though its role in PSCCT is minimal." (PMID 40400806, 2025). "By using thyroid‐specific markers such as thyroglobulin and TTF‐1, IHC helps confirm the presence of thyroid tissue within ovarian tumors, distinguishing MSO from other ovarian neoplasms." (PMID 41356641, 2025). "Pathological examination and IHC analysis provide conclusive evidence for diagnosis, in which the tumor’s positive response to thyroid-specific markers, such as TTF-1, PAX8, and thyroglobulin, is key to diagnosis." (PMID 41244794, 2025). "Thyroid transcription factor‐1 (TTF‐1) was strongly positive (score 3+), reinforcing the presence of thyroid‐originating carcinoma in the ovarian mass." (PMID 41356641, 2025). "TTF-1 is expressed exclusively in thyroid epithelial cells and in bronchioloalveolar cells of the lung; therefore, its expression is used to identify thyroid or pulmonary cancer." (PMID 36672660, 2023). "Pax8 and Ttf1 are transcription factors crucial to thyroid organogenesis, and their absence results in varying degrees of thyroid dysgenesis." (PMID 36765847, 2023). "According to previous reports, the cause of CH in approximately 80%–85% of patients is thyroid dysgenesis (including agenesis, ectopy, and hypoplasia), which is related to gene mutations in TSHR, PAX8, TTF1/NKX2-1, and TTF2/FOXE1." (PMID 37252044, 2023). "We investigated and correlated c-KIT expression levels and two known markers of thyrocytes differentiation, PAX8 and TTF-1, in malignant and benign cytological thyroid samples." (PMID 28301608, 2017). "While positive staining for CK7 is consistent with either agastrointestinal or pulmonary origin of the tumor, TTF-1 positivity is limited to tumors of the thyroid and lung." (PMID 27829227, 2016). "And mutations in thyroid transcription factors TTF-1, TTF-2 and PAX-8 have been implicated in thyroid dysgenesis and abnormal migration of the thyroid bud." (PMID 24748408, 2014). "The study of the cross-talk between Wnt/β-catenin pathway and TTF-1 is of great interest to understand the normal development of thyroid and its transformation into carcinoma." (PMID 21814573, 2011). "TTF-1 plays a very important role in the development, cell growth and differentiation process of thyroid." (PMID 21814573, 2011). "To date, we are unaware of any occult thyroid or pulmonary tumours in our patient to explain the TTF-1 immunoreactivity." (PMID 18492272, 2008). "One study found that in non-small cell lung cancer (NSCLC) patients treated with anti-PD-1 therapy, the expression of thyroid transcription factor-1 (TTF-1) in tumor tissue has been significantly correlated with both the incidence of ICI-induced thyroiditis and the clinical efficacy of ICI therapy." (PMID 40535343, 2025). "TTF-1 is expressed in the thyroid follicle, parathyroid gland, alveolar epithelium, and diencephalon, highlighting its significant application utility in the clinical differentiation of thyroid or pulmonary neoplasms." (PMID 40575170, 2025). "FNA at clavicle mass confirmed a thyroid malignancy (positive for TTF1, thyroglobulin)." (PMID 38791947, 2024). "Increased expression of TTF-1 was found in some thyroiditis patients." (PMID 33042829, 2020). "Therefore, we have also investigated the possible involvement of NKX2.1 (also called TTF-1) in the thyroid pathology of the DKO mice." (PMID 31582725, 2019). "As PAX8 is also expressed in a wide variety of neoplasms from other organs, an initial panel of TTF-1, TG, and PAX8 is needed to confirm or exclude distant metastases from a thyroid primary." (PMID 37324272, 2023).